IL1B (interleukin 1 beta)
Diseases named in the same sentence as IL1B in open-access papers (continued):
Sharing a sentence is not in itself a finding about the gene and the disease.
tumor (continued). "IL-1β activates the NF-κB pathway in tumour cells, inducing the secretion of monocyte chemotactic proteins (MCPs), which further recruit more myeloid cells, forming a vicious cycle of angiogenesis and immune suppression." (PMID 40630800, 2025). "The glioma microenvironment is enriched with pro-inflammatory cytokines, such as IL-1β, IL-6, and TNF-α, along with tumor-associated macrophages (TAMs) and microglia." (PMID 40881678, 2025). "Due to local swelling and inflammatory processes, pro-inflammatory factors, including interleukin-1β (IL-1β), also act in the area of the tumor." (PMID 40429943, 2025). "Our results demonstrated that IL-6, IL-1β, and IL-10 were overexpressed in tumor tissues compared with normal mucosa." (PMID 41267807, 2025). "This inhibitory effect led to a marked decrease in gene expression of pro-inflammatory factors including IL6, IL8 and IL1B, reducing the pro-inflammatory state within tumor microenvironment." (PMID 40535567, 2025). "Tumor co-culture induced further enhancement of M1-associated markers including CD80/CD86, MHC-II and IL-1β/IL-6/TNF-α/IL-12/IFN-γ, while suppressing M2 markers CD163/CD206, indicating tumor-triggered M1 polarization." (PMID 41388305, 2025). "This led to a substantial increase in intratumoral and systemic IL-1β concentrations, enhancing tumor-specific IFNγ-mediated CD8+ T cell responses." (PMID 41209313, 2025). "Anti-IL-1β monoclonal antibody significantly enhanced the anti-tumor activity of anti-PD-1 in a preclinical model of PDAC." (PMID 39948655, 2025). "In this study, we present the results of a large retrospective database analysis examining the relationship between tumor IL-1β expression and survival outcomes in NSCLC patients, particularly those with actionable oncogenic mutations." (PMID 40940992, 2025). "The role of IL-1β in tumor development, survival, and metastasis has been well established, and some examples have been discussed earlier in this review." (PMID 39858071, 2025). "The study also identified that tumor cell expression of IL-1β is driven by microbial-dependent activation of toll-like receptor 4 (TLR4) signaling and subsequent engagement of the NLRP3 inflammasome." (PMID 39948655, 2025). "The mRNA expression of tumor-supportive macrophage genes, such as Arg-1, was reduced by shTRIM32-CM, whereas the expression of cytotoxic response genes IL-1β, IL-12 A, and CD86 was elevated by shTRIM32 cell supernatants." (PMID 41163195, 2025). "IL-1β is known to promote the differentiation and expansion of Th17 cells, which in turn can enhance tumor growth, angiogenesis, and metastasis 46-49." (PMID 41209556, 2025). "The TTFields and anti-PD-1 treatment group induced more release of IL-1β and IL-18 in tumor than anti-PD-1 treatment alone." (PMID 40098106, 2025). "An inflammatory feedback loop has been identified between TAMs expressing interleukin-1β (IL-1β) and tumor cells, which serves as a precursor to pancreatic carcinogenesis." (PMID 40948749, 2025). "Monocytes and macrophages, the main tumor-infiltrating cells, produce cytokines like IL-1β, IL-6, IL-23, and TNF-α, playing a crucial role in cancer progression within an inflammatory context." (PMID 40430101, 2025). "Tumor-associated inflammation, characterized by elevated TNF-α, IL-6, and IL-1β, was effectively suppressed in both colon tissue and systemic circulation." (PMID 41199821, 2025). "In this line, IL-1β increases tumor progression in murine models and is considered a mediator of chronic non-resolving inflammation linked to gastrointestinal tract malignancies." (PMID 39305371, 2025). "To assess the impact of combination anti-IL-1β and anti-PD-1 treatment on primary tumor growth, we utilized a previously established KPC orthotopic murine model of PDAC." (PMID 39948655, 2025). "In further preclinical models, IL-1β blockade has shown potential to interrupt tumor-promoting inflammation, modulate the TME toward an immune-activated status, and synergize with ICIs." (PMID 40116353, 2025).
tumor (continued). "IL6 and IL1B were significantly upregulated in tumor tissues compared with matched normal mucosa (p < 0.05)." (PMID 41267807, 2025). "Persistent pyroptosis leads to sustained activation of NLRP3 inflammasomes, driving IL-1β overproduction, angiogenesis, and stromal remodeling, thereby creating an ecological niche for tumor metastasis." (PMID 41267084, 2025). "Notoriously, the CRC microenvironment is characterized by elevated levels of several pro-inflammatory cytokines, among which IL-1β, considered the major mediator of inflammation, stands out and fuels tumor invasion through immunosuppressive activities." (PMID 40869063, 2025). "Overall, IL-1β essentially “supercharges” the tumor microenvironment into a highly inflammatory state that favors tumor cell migration, immune evasion, and metastasis." (PMID 41007766, 2025). "Similarly, IL-1β-deficient mice injected orthotopically with BC cells showed initial tumor growth, followed by regression linked to recruitment of alternative inflammatory monocytes and increased IL-12 secretion, promoting anti-tumor immunity and CD8+ T-cell activation." (PMID 40868199, 2025). "STING activation led to IL-18 and IL-1β secretion of macrophages, which enhanced the anti-tumor capability of NK cell by inducing 4-1BBL expression in macrophage and 4-1BB in NK cell, respectively." (PMID 40075527, 2025). "Activation of MAPK and NF-κB converges on inflammatory mediators and tumor-promoting genes such as IL1B, which facilitate tumor initiation, fibroblast activation, angiogenesis, EMT, and immune suppression." (PMID 41510255, 2025). "IL-1β cytokine production is needed to activate the anti-tumour immune response and polarize the CD8+ T lymphocytes that produce IFN-γ." (PMID 41228271, 2025). "Inflammatory mediators such as IL1β, IL6, and MCP-3 (CCL7) not only drive SCC cell growth but also recruit and condition myeloid populations, including monocytes, tumor-associated macrophages, and MDSCs, thereby promoting a suppressive, tumor-permissive niche." (PMID 41510255, 2025). "The investigators demonstrated that production of IL-1β by lung macrophages promotes expansion of mutant cells and that inhibition of IL-1β using neutralizing antibodies prevented PM-promoted tumor formation." (PMID 40892514, 2025). "In the HIF-1 signaling pathway, hypoxia-inducible factor HIF1A is produced under hypoxic conditions, which drives the secretion of IL1B to enhance tumor cell proliferation, migration, and invasion." (PMID 40725477, 2025). "Given IL-1β’s role as a potent pro-inflammatory cytokine and contributor to tumor-promoting inflammation, angiogenesis, and immune evasion, its suppression by the combination therapy suggests a favorable immunomodulatory effect." (PMID 41401147, 2025). "The evidence provided above strongly supports a crucial role of IL-1β in promoting tumor growth and progression." (PMID 39858071, 2025). "Adenosine also inhibits the ability of neutrophils to produce pro-inflammatory cytokines such as TNF-α and IL-1β, further contributing to an immunosuppressive environment that favors tumor growth." (PMID 40486614, 2025). "Cytokine analysis further revealed that TNF-α and IL-1β—key effectors of NK-mediated tumor cell killing and pyroptosis—were substantially reduced in the absence of NK cells." (PMID 41239499, 2025). "Within the tumor microenvironment, IL-1β acts on endothelial cells, fibroblasts, and immune subsets to promote angiogenesis, recruit immunosuppressive myeloid cells, and sustain chronic inflammation that facilitates tumor progression." (PMID 40940992, 2025). "This dysfunction is mediated by a pro-inflammatory tumor microenvironment, where cytokines such as IL-1β, IL-6, IFN-γ, and TNF-α activate Toll-like receptors (TLRs), promoting taste bud apoptosis and impairing cellular turnover." (PMID 40868108, 2025). "And IL1B promoted tumor invasion and growth by inducing production of various pro-inflammatory factors and enhancing inflammatory responses." (PMID 40535567, 2025).
tumor (continued). "IL-1β is central to inflammasome activation and tumor-promoting inflammation via NLRP3 and NF-κB signaling." (PMID 41401147, 2025). "Studies have shown that IL-1β of TME promotes tumor progression through increasing CXCL13 expression and infiltration of immune-suppressive IL-35+ B cells." (PMID 39744696, 2025). "Nevertheless, the combination of anti-PD-1 and anti-IL-1β treatments resulted in similar modulations of the cytokine/chemokine ligand-receptor interactions as compared to anti-IL-1β treatment in the KPC-4545 tumor." (PMID 39948655, 2025). "What appears to be more unique for the KPC-3403 model compared to the KPC-4545 model is the smaller number of CAFs in the untreated control tumor and the increase of CAFs following anti-IL-1β treatment." (PMID 39948655, 2025). "Compared with paired surgical margins, tumour tissues exhibited an inflammatory shift characterised by increased IL-1β and IL-6 alongside reduced TNF-α, IFN-γ, IL-12 and IL-2." (PMID 41465261, 2025). "In summary, during efferocytosis, downstream effects of NLRP3/Caspase‐1/IL‐1β signaling axis in macrophages promote tumor growth in vivo." (PMID 39748782, 2025). "IL-1β promotes the expression of adhesion molecules, cytokines, and growth factors that support tumor expansion and infiltration into adjacent brain tissue." (PMID 40565357, 2025). "Tumor-associated macrophage (TAM) derived cytokines such as VEGF and CCL8 promote angiogenesis and tumor progression, while NLRP3/IL-1β expression in TAMs is associated with reduced survival and increased lymph node metastasis in HER2+ patients." (PMID 41373809, 2025). "GSDME-mediated pyroptosis significantly increases tumor infiltration of CD8+ T cells by releasing IL-1β and IL-18, effectively reprogramming the immunosuppressive TME." (PMID 41267084, 2025). "FcγRI‐CAR‐HMs treatment shifted tumor‐associated macrophages (TAMs) from an immunosuppressive to immunostimulatory phenotype, evidenced by upregulated CD86/IL‐1β/IL‐12/TNF‐α and downregulated CD206/TGF‐β." (PMID 40847445, 2025). "2L4-8 treatment also suppressed IFN-β response pathways (downregulation of IL1a, IL1b) and tumor development-related HIF-1 signaling, while enhancing the antigen presentation-related pathway." (PMID 40695812, 2025). "In luminal BC, IL-1β promotes the production of IL-6 through the NF-κB signaling pathway, which leads to tumor growth and increased malignancy." (PMID 40251177, 2025). "Numerous studies have shown that M1 macrophages can express TNF-α, IL-1β, IL-6, IL-12, and IL-23, directly acting on tumor cells and promoting a Th1 response to inhibit tumors." (PMID 40102723, 2025). "And curcumin suppresses tumor migration and proliferation by interfering with IL1B and its downstream pathways." (PMID 40535567, 2025). "They contribute to tumor development through the release of IL-1β, yet also secrete CCL17 to recruit regulatory T cells, facilitating immune evasion, and support angiogenesis." (PMID 41299673, 2025). "Lactic acid secreted by tumor cells into macrophages promotes the secretion of IL-1β from even cells, and IL-1β induces an immunosuppressive phenotype in tumor cells." (PMID 40165895, 2025). "IL1B, as a pro-inflammatory cytokine, played an essential role in chronic inflammation and tumor growth (Rébé and Ghiringhelli, 2020)." (PMID 40535567, 2025). "IL-1β blockade has the potential to interrupt tumor-promoting inflammation, shift the tumor immune microenvironment toward an immune-activated status, and synergize with ICIs." (PMID 40116353, 2025). "During inflammation, MMPs increase both directly and via IL-1β, playing a crucial role in the invasion and migration of tumor cells by degrading the extracellular matrix and cell-cell junctions." (PMID 40453286, 2025). "In the tumor microenvironment, IL-1β induces G-CSF production, promoting both neutrophil expansion and functional polarization." (PMID 40564191, 2025).
tumor (continued). "Specifically, IL-1RA, an effective antagonist of IL-1, competitively binds to the IL-1 receptor, thereby inhibiting the pro-inflammatory effects of IL-1β and modulating inflammation and tumor activation processes." (PMID 40136462, 2025). "These factors then synergistically drive monocyte differentiation into IL-1β+ TAMs, establishing a self-amplifying circuit that perpetuates tumor progression." (PMID 40948749, 2025). "Under chemoradiotherapy, cytokines like TGF‐β, IL‐1β are released from tumor cells, which can be internalized by immune cells to reprogram cellular metabolism and trigger senescence." (PMID 41427020, 2025). "Salmonella typhimurium VNP20009 requires slyA, STM3120, and htrA genes for tumor colonization and immune activation via TNF-α/IL-1β induction, though its clinical translation has been limited by attenuated tumor colonization in humans." (PMID 40297102, 2025). "The role of inflammatory factors IL-1b and IL-8 in tumor cell proliferation and metastasis has been demonstrated through their regulation of apoptosis within the tumor microenvironment." (PMID 40487760, 2025). "Increasing and convincing evidence shows that IL-1β can also be expressed by cancer cells, indicating a tumor-autonomous role in fueling neoplastic progression, either together with or independently of the immune system." (PMID 39858071, 2025). "Tumor‐derived IL‐1α mediates the polarization of HSCs into inflammatory fibroblasts, which subsequently produce complement C5a and IL‐1β, promoting neutrophil infiltration and the release of NETs." (PMID 40027151, 2025). "Single-nuclear RNA sequencing analysis of both organ-specific tumor models demonstrated that anti-IL-1β treatment altered infiltration and function of CAF and immune cells differently." (PMID 39948655, 2025). "This suggests that IL-1β fosters resistance to checkpoint inhibitors, and its removal can “unmask” an anti-tumor immune response." (PMID 41007766, 2025). "While M2 macrophages promote tumor growth, angiogenesis, and immune suppression, M1 macrophages foster inflammation and induce tumor cell death by releasing cytotoxic molecules (e.g., IL-1β, IL-6, caspases)." (PMID 40870970, 2025). "Tregs sequester available IL-1β in the tumor microenvironment (TME), a mechanism that positions IL-1R2 as an active orchestrator of tumor immune escape." (PMID 41415279, 2025). "NLRP3 levels and downstream effectors, like caspase-1 and IL-1β, can be measured as direct biomarkers and surrogate biomarkers by immunohistochemistry, qRT-PCR in tumor tissues of biofluids." (PMID 41560727, 2025). "GBM growth is significantly accelerated by IL-1β, a cytokine highly expressed in TAMs and neutrophils localized in the perinecrotic tumor areas." (PMID 38397187, 2024). "Here, the mRNA levels of proinflammatory cytokines Tnfa, Il6, Il1b as well as the chemokine Ccl2 were significantly higher in Plg− tumors relative to Plg+ tumors consistent with the smaller tumor size and increased levels of apoptosis." (PMID 37971174, 2024). "Clinical tumor progression and metastasis are affected by a complex environment that includes an accumulation of inflammatory cytokines such as IL1β and TNFα that, in turn, target the tumor cells." (PMID 39199704, 2024). "Our results suggest that the production of MC4 is due to the presence of many ILB+ macrophages at the tumor-normal interface, which secrete IL-1β that acts on ADRB2 on VEGFA+ MCs." (PMID 39840068, 2024). "We showed that fibroblasts activated through tumor-bearing derived EVs showed upregulated expression levels of multiple inflammatory cytokines, such as IL-1β, IL-6, IL-8, TNF-α, and TGF-β, in a time-dependent manner." (PMID 39056778, 2024). "Specifically, IL1β activates NF-κB in tumour cells, inducing the expression of programmed death-ligand 1 (PD-L1), which then induces T cell exhaustion." (PMID 39315158, 2024).
tumor (continued). "A previous study showed that radiotherapy increased the expression of cytokine IL-1β in the spleen and slowed down tumor growth in a mouse model." (PMID 38340166, 2024). "The simultaneous expression of ZFP36L2 and IL1β in IL1β+ macrophages suggests a pivotal role of macrophages in the production of cytotoxic effects against tumor cells and the enhancement of prognosis." (PMID 39767767, 2024). "TNBC-related inflammation is also confirmed by the statistically increased release of IL-1β by tumor cells compared to normal cells (p < 0.01)." (PMID 39433537, 2024). "Under cancer conditions, large numbers of IMCs can be pathologically activated by tumour-derived factors such as IL-6 and IL-1β to differentiate into MDSCs." (PMID 39156102, 2024). "The anti-tumor effect of IL-10 has been demonstrated in various tumor models through the activation of T cells, partially demonstrating the anti-tumor role of IL1B+ TAMs." (PMID 39232806, 2024). "Within a lung cancer model, local microbiota activated neutrophil release of IL-1β and IL-23, inducing lung-resident γδ T cells that promoted inflammation and tumor growth." (PMID 38474175, 2024). "NALP1 is part of the NLRP1 inflammasome, which can induce the maturation and secretion of IL-1β, activate inflammatory responses, and promote tumor growth and spread." (PMID 38780447, 2024). "Even though these two cytokines comparably transduce signaling, the role of IL-1α has been debated, but IL-1β was shown to promote tumor growth in cancer." (PMID 39201290, 2024). "Studies have shown that inflammatory cytokines such as TNF-α, IL-6, and IL-1β can activate cellular signaling pathways that promote tumor survival and growth." (PMID 39339213, 2024). "Several cytokines, including TNF-α, IL-10, IL-17, and IL-1β, have been shown to play an important role in the tumor inflammatory environment or tumor immune response." (PMID 38734702, 2024). "This secretion, in turn, enhances tumor cell motility and invasiveness through the activation of the IL-1β-NFκB signaling pathway." (PMID 39801513, 2024). "Through secretion of chemokines and effector molecules such as c-x-c chemokine ligand 5 (CXCL5), IL-1β, matrix metalloproteinases (MMPs), and collagen, CAFs contribute to immunosuppression and tumor angiogenesis." (PMID 38292868, 2024). "A well-described mechanism is that during aging, hepatic stellate cells adopt aging-related changes and secrete various inflammatory and tumor-promoting factors, including IL-1β, IL-6 and CXCL7, to induce neutrophil infiltration." (PMID 38539791, 2024). "TANs can induce tumor cell invasion and migration through various ways, in which IL-1β occupies an eminent position." (PMID 38590651, 2024). "Immune-phenotyping of Pten-deficient prostates revealed high accumulation of tumor-infiltrating leukocytes, particularly innate immune cells, neutrophils and macrophages as well as high levels of STAT3 activation and IL-1β production." (PMID 38811984, 2024). "Pro-inflammatory cytokines, such as interleukin (IL)-1β, IL-6, and IL-8, can classically activate macrophages to the M1 phenotype, mounting an anti-tumor immune response." (PMID 39256888, 2024). "Aberrant activation of NLRP3 within the tumor microenvironment results in increased IL-1β and IL-18 secretion." (PMID 39882243, 2024). "Mechanistically, neutralization of IL‐17, produced by γδ T cells, decreases infiltration of neutrophils and tumor burden with significant reduction of IL‐1β levels." (PMID 38703051, 2024). "In the tumor tissue of the TH animals, high expression of Nfkb, Il1b, and Il6 was observed, accompanied by high Tgfb and Il10 expression in the peritumoral area." (PMID 39063041, 2024). "These recruited M‐MDSCs release IL‐1β even before the arrival of tumor cells which increases the expression of E‐selectin in the endothelial cells and tumor cell adherence." (PMID 38703051, 2024).